SLC5A2 (solute carrier family 5 member 2)
Diseases named in the same sentence as SLC5A2 in open-access papers (continued):
Sharing a sentence is not in itself a finding about the gene and the disease.
COVID-19 (69 papers, 2020 to 2025). A disease caused by infection with severe acute respiratory syndrome coronavirus 2. "Our study suggests that SLC5A2 is elevated in fibroblasts and positively correlates with myofibroblast, predicting that SLC5A2 is target of COVID-19 related-fibrosis." (PMID 38144556, 2023).
coronary artery disease (65 papers, 2019 to 2025). "Furthermore, their genetic risk analysis for SLC5A2 variants showed decreased HF risk for each additional allele inherited, with a more pronounced effect in patients without T2DM or coronary artery disease." (PMID 40356983, 2025). "We explored whether SLC5A2 SNPs were associated with (i) fasting glucose, the post-challenge glucose increase in oral glucose tolerance tests and HbA1c; (ii) the prevalence of T2DM, and (iii) baseline coronary artery disease (CAD) as well as incidence of cardiovascular events during follow-up." (PMID 30988077, 2019).
liver fibrosis (40 papers, 2016 to 2026). "Mendelian randomization (MR) was performed using single-nucleotide polymorphisms (SNPs) within the SLC5A2 locus as genetic instruments to evaluate the causal effect of SGLT2 inhibition on liver fibrosis and cirrhosis." (PMID 41150795, 2025).
familial renal glucosuria (33 papers, 2012 to 2025). Familial Renal Glucosuria (FRG) is characterized by the presence of persistent isolated glucosuria in the absence of both generalized proximal tubular dysfunction and hyperglycemia. "Although the mode of inheritance for renal glucosuria remains complex, 2.0% of an ethnically diverse population carry rare variants in SLC5A2 that are likely risk factors of this understudied trait." (PMID 39412882, 2025). "On the basis of population data, 2% of an ethnically diverse population carried rare variants in SLC5A2 and are at risk of renal glucosuria." (PMID 39412882, 2025). "Renal glucosuria is a rare inheritable trait caused by loss-of-function variants in the gene that encodes sodium-glucose cotransporter-2 (SGLT2) (i.e., SLC5A2)." (PMID 39412882, 2025). "To study the genetics of renal glucosuria, we evaluated all SLC5A2 coding variants sequenced in 245,394 participants enrolled in AoU." (PMID 39412882, 2025). "To identify potentially novel SLC5A2 variants associated with renal glucosuria, we screened all protein altering variants provided there were at least two individuals in the cohort with the variant (n=357 variants)." (PMID 39412882, 2025). "There are patients with familial renal glucosuria that have mutations in the solute carrier family 5 member 2 (Slc5a2) gene encoding SGLT2." (PMID 37047250, 2023). "Dominant mutations in SLC5A2, which encodes the sodium glucose co-transporter 2 (SGLT2), lead to familial renal glucosuria (FRG)." (PMID 35422763, 2022). "Familial renal glucosuria (FRG) is a rare renal tubular disorder caused by autosomal recessive mutations in gene SLC5A2 coding the SGLT2 sodium-dependent glucose co-transporter." (PMID 34948317, 2021). "Heterozygous mutations in SLC5A2, which encodes the sodium glucose co-transporter 2 (SGLT2), cause familial renal glucosuria (FRG)." (PMID 33849624, 2021). "Recently, some studies have confirmed that SLC5A2 mutations are responsible for the pathogenesis of familial renal glucosuria, but FRG cases are still rare." (PMID 32111189, 2020). "In our previous and current studies, fourteen novel variants in SLC5A2 were identified in twenty-two Chinese renal glucosuria families and confirm previous observations that most variants were private mutations." (PMID 32111189, 2020). "SLC5A2 encodes the sodium-dependent glucose transport protein solute carrier family 5, member 2, dysfunction of which is associated with renal glucosuria." (PMID 26398943, 2015). "Various mutations within the SLC5A2 (solute carrier family 5 member 2) gene, which encode SGLT2, have been associated with familial renal glucosuria, characterized by unusually elevated urinary glucose excretion even in the presence of normal blood glucose levels." (PMID 38473908, 2024). "In conclusion, a novel SLC5A2 variant was identified in a family with familial renal glucosuria." (PMID 36450716, 2022). "Familial renal glucosuria is a rare renal tubular disorder caused by SLC5A2 gene variants." (PMID 33250922, 2020). "Indeed, in a cohort of familial renal glucosuria primarily composed of patients with inactivating mutations in SLC5A2 encoding the renal glucose transporter SGLT2, one patient was found to have a mutually exclusive homozygous truncating mutation in PDZK1IP112,47." (PMID 36253360, 2022). "This study identified a novel mutation in the SLC5A2 gene related to a benign clinical characteristic and suggests that the molecular diagnosis of the SLC5A2 gene may be useful for diagnosing renal glucosuria in patients and for deciding intervention measures for their family members." (PMID 24255686, 2013). "One prominent example is the development of blockbuster SGLT2 (encoded by SLC5A2) inhibitors for the treatment of diabetic hyperglycaemia, which was inspired by associations between SLC5A2 mutations and familial renal glucosuria (OMIM identifier 233100)." (PMID 31679053, 2019).
familial renal glucosuria (continued). "There are at least 50 autosomal dominant and autosomal recessive mutations in the SGLT2 coding gene (SLC5A2), underlying familial renal glucosuria (FRG)." (PMID 31554505, 2019).
ischemic stroke (28 papers, 2019 to 2025). A stroke disorder caused by obstruction of blood flow to the brain, due to thrombotic (local blood clot formation) or embolic (due to a blood clot or other material traveling from another site) event. "Our findings suggest that elevated SLC5A2 and KCNJ11expression levels are associated with an increased risk of ischemic stroke." (PMID 41209129, 2025). "Our study revealed that a greaterrisk of ischemic stroke was linked to higher SLC5A2 gene expressionlevels." (PMID 41209129, 2025). "Specifically, increased expression of KCNJ11 (the targetgene of sulfonylureas) and SLC5A2 (the target gene of SGLT2 inhibitors)was associated with a heightened risk of ischemic stroke." (PMID 41209129, 2025).
prostate carcinoma (24 papers, 2019 to 2026). A carcinoma that arises from epithelial cells of the prostate gland. "Sensitivity MR analyses in which we removed variants within the SLC5A2 region showed similar effects to those seen in our analyses of HbA1c on prostate cancer." (PMID 39168098, 2024). "The exchangeability MR assumption was tested using genetic colocalization between SGLT2 inhibition and prostate cancer, where we observed evidence of colocalization of the two traits in the SLC5A2 region (colocalization probability = 72%)." (PMID 39168098, 2024).
hyperlipidemia (22 papers, 2017 to 2025). "Linear regression analysis controlling for sex, hyperlipidaemia, CCIMT and CKD stage, showed that two SNPs in SLC2A1 (coding for the GLUT1 transporter), rs841848 and rs710218, and the rs3813008 variant in SLC5A2 (coding for SGLT2) were associated with eGFR values." (PMID 36314849, 2022).
depression (21 papers, 2019 to 2026). "These include, among others, the GABA transporter GAT1 for epilepsy, the serotonin transporter SERT for depression, and the sodium‐glucose co‐transporter SGLT2 (SLC5A2) for DM." (PMID 41542789, 2026).
diabetic retinopathy (21 papers, 2016 to 2026). "A total of 181 patients with T2D were genotyped for SLC5A2 rs9934336 G>A polymorphism and monitored for kidney function and diabetic retinopathy." (PMID 33974529, 2021). "This is also the first report on the association between SLC5A2 polymorphism and diabetic retinopathy." (PMID 33269015, 2020). "Furthermore, they found that SLC5A2 rs9934336 G>A polymorphism is significantly associated with the risk of diabetic retinopathy." (PMID 33974529, 2021). "Furthermore, we report for the first time a biologically plausible association between SLC5A2 polymorphism and diabetic retinopathy." (PMID 33269015, 2020). "After adjustment for T2D duration, significantly higher risk for diabetic retinopathy was present in carriers of at least one polymorphic SLC5A2 rs9934336 A allele compared to non-carriers (OR=7.62; 95%CI=1.65-35.28; P=0.009)." (PMID 33269015, 2020). "Carriers of at least one polymorphic SLC5A2 rs9934336 A allele had nominally significantly higher risk for diabetic retinopathy than non-carriers (OR=7.62; 95%CI=1.65-35.28; P=0.009)." (PMID 33269015, 2020). "However in our study we observed an interesting association of SLC5A2 rs9934336 poly morphism and the risk for development of diabetic retinopathy, but no other associations with either other microvascular or macrovascular late complications of T2D." (PMID 33269015, 2020).
pancreatic cancer (21 papers, 2018 to 2025). "SLC5A2 was connected with pancreatic cancer (OR: 8.096; 95% CI: 3.476–18.857; P-value < 0.0001)." (PMID 38504335, 2024). "Furthermore, there were evidences uncovering the associations between SLC5A2 and cardia cancer (OR = 13.666; 95% CI: 4.610-40.515; P-value < 0.0001), HCC (OR = 29.465; 95% CI: 6.568-132.195; P-value < 0.0001), and pancreatic cancer (OR = 8.096; 95%CI: 3.476–18.857; P-value < 0.0001)." (PMID 38504335, 2024). "Associations of ABCC8/KCNJ11, DPP4, GLP1R, GPD2, PPARG, PRKAB1, and SLC5A2 with anal carcinoma, cardia cancer, gastric cancer, HCC, ICC, pancreatic cancer, and rectum cancer were revealed in two-sample MR analyses." (PMID 38504335, 2024).
ischemia (18 papers, 2019 to 2024). A hypoperfusion of the BLOOD through an organ or tissue caused by a PATHOLOGIC CONSTRICTION or obstruction of its BLOOD VESSELS, or an absence of BLOOD CIRCULATION. "Further work will be required to identify the transcriptional mechanism responsible for Slc5a2/SGLT2 upregulation in astrocytes post-ischemia." (PMID 37759444, 2023).
renal glycosuria (11 papers, 2015 to 2024). An autosomal inherited disorder due to defective reabsorption of GLUCOSE by the PROXIMAL RENAL TUBULES. "Case 2 had pathogenic rare mutation ivs7 + 5G > A in the SLC5A2 gene, which has been reported as a hot spot mutation causing hereditary renal glycosuria." (PMID 35229480, 2022). "Here, we reported long‐term follow‐up of two diabetic cases with hereditary renal glycosuria caused by SLC5A2 mutations and they were still responsive to SGLT2 inhibitor treatment." (PMID 35229480, 2022). "Here, we report two diabetic patients with hereditary renal glycosuria caused by SLC5A2 gene mutations." (PMID 35229480, 2022). "Nevertheless, the discovery that familial renal glycosuria is caused by genetic variants in the gene encoding SGLT2 (SLC5A2) provided an opportunity to test for any side effects of long-term perturbations." (PMID 28447115, 2017). "In conclusion, mutations in the SLC5A2 gene were the most likely cause of renal glycosuria in this family." (PMID 26735923, 2016). "Familial renal glycosuria (FRG) is caused by mutations in the SLC5A2 gene, which codes for Na+-glucose co-transporters 2 (SGLT2)." (PMID 27666404, 2016). "rs13337037 lies 15 kb upstream of SLC5A2 and, while it is difficult to assert a direct relationship between neighbouring loci and signal at specific SNPs, evidence has implicated SLC5A2 in familial renal glycosuria." (PMID 32227112, 2020). "Loss of function mutations in SGLT2 coding gene SLC5A2 has been known to lead to familial renal glycosuria, without affecting the lifespan of the patients." (PMID 38837668, 2024).
Impaired glucose tolerance (7 papers, 2020 to 2025). An abnormal resistance to glucose, i.e., a reduction in the ability to maintain glucose levels in the blood stream within normal limits following oral or intravenous administration of glucose. "Modest association of SLC5A2 rs9934336 polymorphism with glucose concentrations during oral glucose tolerance test was also observed in a cohort of German Sorb nondiabetic individuals with either normal glucose tolerance, impaired fasting glucose or impaired glucose tolerance." (PMID 33269015, 2020).
coronary atherosclerosis (5 papers, 2019 to 2025). Atherosclerosis of the coronary vasculature. "Moreover, the association between SLC5A2 variants and coronary atherosclerosis as well as with the risk of future cardiovascular events is unclear." (PMID 30988077, 2019). "Neither in non-diabetic subjects nor in patients with T2DM SLC5A2 SNPs were significantly associated with the prevalence of significant coronary atherosclerosis or the incidence of future vascular events." (PMID 30988077, 2019). "Of note, the Bonferroni correction would probably have been too conservative owing to the given close correlation among included SLC5A2 SNPs and investigated phenotypes (T2DM, coronary atherosclerosis, cardiovascular events)." (PMID 30988077, 2019).
skin cancer (3 papers, 2024 to 2026). "Besides, our findings did not support the antidiabetic drug target perturbations, apart from SLC5A2, in relation to skin cancer risk." (PMID 39640975, 2024). "Currently, there is limited investigation into the mechanisms by which SGLT-2 inhibition via the SLC5A2 target may influence skin cancer risk." (PMID 39640975, 2024). "Notwithstanding contradicting one prior study, our findings align with a meta-analysis that did not support the effect of SGLT-2 inhibitors targeting SLC5A2 on the risk of skin cancer in patients with T2D." (PMID 39640975, 2024).
basal cell carcinoma (2 papers, 2024 to 2026). A carcinoma involving the basal cells. "The evidence supporting a shared causal variant between HbA1c levels and basal cell carcinoma at the SLC5A2 locus is relatively weak (PP.H4 < 0.80)." (PMID 39640975, 2024). "Furthermore, there was limited evidence that HbA1c and basal cell carcinoma share common causal variants in SLC5A2." (PMID 39640975, 2024). "Moreover, the promoted impact of perturbation of the antidiabetic drug target SLC5A2 on the risk of basal cell carcinoma was also confirmed." (PMID 39640975, 2024). "The study also discovered that perturbation of the antidiabetic drug target SLC5A2 was significantly associated with an increased risk of basal cell carcinoma (for SLC5A2 perturbation equivalent to a 6.75 mmol/mol decrement in HbA1c: OR: 2.004, 95% CI: 1.270–3.161, p = 0.0027)." (PMID 39640975, 2024). "While our MR study unveiled a noteworthy interplay between genetically proxied SLC5A2 perturbation and an elevated risk of basal cell cancer, the colocalization analysis failed to substantiate this finding." (PMID 39640975, 2024). "Additionally, we identified that the perturbation of the antidiabetic drug target SLC5A2 has a significant impact on elevating the risk of basal cell carcinoma, yet this was not supported by colocalization evidence." (PMID 39640975, 2024).
migraine (2 papers, 2024). "This activation, in turn, influences other proteins like RAMP 1–3, CALCB, CALCR, and SLC5A2, which are implicated in migraine attacks." (PMID 39215033, 2024). "OPRM1 emerges as a pivotal hub, instigating the activation of GNAS and GNB1, subsequently influencing proteins such as RAMP1, RAMP2, RAMP3, CALCB, CALCR, and SLC5A2 all implicated in migraine attacks." (PMID 39215033, 2024).
Epileptic seizures (1 paper, 2020). "Epileptic seizures were also present in families with NAGLU, SLC5A2, POLR3B, and VPS13A mutations, and behavioral and psychiatric symptoms were observed in a family with POLR3B mutations (Fam 03)." (PMID 31969655, 2020).
hemoglobinuria (1 paper, 2024). A laboratory test result which indicates free hemoglobin in the urine. "In addition, the SGLT2 instruments showed associations with the expression of 17 genes excluding SLC5A2, with two genes being targets for existing drugs for coagulation and hemoglobinuria treatment." (PMID 39168098, 2024).
mucinous ovarian cancer (1 paper, 2026). An invasive malignant neoplasm that arises from the ovary and is characterized by the presence of malignant epithelial cells that contain intracytoplasmic mucin and may resemble the epithelial cells of the endocervix or gastrointestinal tract. "We then performed cis drug-target MR for PPARG, DPP4, ABCC8/KCNJ11, and SLC5A2, integrated triangulation, colocalization, and mediation analyses, and experimentally interrogated the prioritized PPARG/ABCC8-KCNJ11-lactate-invasive mucinous ovarian cancer (IMOC) triangle." (PMID 42278567, 2026).
cardiovascular disease (366 papers, 2014 to 2026). "So far, a link between common genetic variations of the SGLT2 encoding gene SLC5A2 and glucose homeostasis as well as cardiovascular disease has not been established." (PMID 30988077, 2019).
cancer (169 papers, 2013 to 2026). A tumor composed of atypical neoplastic, often pleomorphic cells that invade other tissues. "The gene expression of SLC5A1 and SLC5A2 and the protein expression of SGLT1 and SGLT2 have increased in several cancer cell lines and human cancer tissues." (PMID 39940750, 2025). "In our analysis of the TCGA database, we found that SLC5A1 and SLC5A2 gene expression increased in CCA, consistent with the findings observed in other types of cancers." (PMID 39940750, 2025).
tumor (86 papers, 2014 to 2026). "In the GEO dataset, the expression level of SLC5A2 mRNA in tumour tissue was significantly lower than that in normal tissue in the three series (all P < 0.001)." (PMID 35090421, 2022). "In the present xenograft study, we demonstrated that a combination treatment of sorafenib and canagliflozin (which inhibits the glucose transporter SLC5A2) significantly retarded HCC xenograft tumor growth." (PMID 36385558, 2022). "Here, we investigated the oncogenic effect of SLC5A2 on the colorectal mucosal epithelium using transgenic rats and an azoxymethane/dextran sulphate sodium (AOM/DSS)-induced tumour model." (PMID 41968633, 2026). "In the Oncomine database, SLC5A2 mRNA levels were lower in tumour tissue in both datasets (not significant)." (PMID 35090421, 2022).
metabolic disease (45 papers, 2016 to 2026). A congenital disorder (due to inherited enzyme abnormality) or acquired (due to failure of a metabolically important organ) disorder resulting from an abnormal metabolic process. "Transcriptome-wide analyses further support this concept, showing decreased SLC5A2 expression in advanced metabolic disorder-associated CKD and strong associations with fibrosis-related gene programs." (PMID 41596241, 2026).
retinopathy (14 papers, 2020 to 2025). "Retinopathy was the only late T2D complication associated with SLC5A2 polymorphism after adjustment for T2D duration." (PMID 33269015, 2020).
connective tissue disease (2 papers, 2018 to 2024). "Herein, we report an unusual case of isolated renal glucosuria in an undifferentiated connective tissue disease (UCTD) patient with a heterozygous mutation in SLC5A2." (PMID 30558067, 2018).
SLC5A2 also shares sentences with these, for which no sentence is quoted: chronic kidney disease (607 papers); kidney disease (349); myocardial infarction (203); acute kidney injury (163); Stroke (162); diabetic ketoacidosis (161); Insulin resistance (159); type 1 diabetes (127); urinary tract infection (127); chronic heart failure (105); atherosclerosis (81); dyslipidemia (75); kidney failure (74); Nephropathy (68); endothelial dysfunction (61); acute myocardial infarction (59); infection (57); Arrhythmia (53); Hyperkalemia (53); non-alcoholic fatty liver disease (47); anemia (41); dementia (41); diabetic cardiomyopathy (41); cardiomyopathy (39); breast carcinoma (37); sarcopenia (37); hepatocellular carcinoma (35); heart disease (34); hyperuricemia (34); liver disease (34).
A further 526 diseases each share a sentence with SLC5A2 in 33 papers or fewer.